HIF1A (hypoxia inducible factor 1 subunit alpha)
Diseases named in the same sentence as HIF1A in open-access papers (continued):
Sharing a sentence is not in itself a finding about the gene and the disease.
tumor (continued). "Numerous studies have consistently confirmed that CO2 therapy will decrease the size of tumors by reducing the hypoxic core of the tumor, reversing the stabilization of HIF-1α to modulate survival pathways, and triggering non-HIF-related pathways." (PMID 36982254, 2023). "Importantly, TEPP-46 treatment attenuated the expression of HIF-1α, HK2, and PKM2, an diminished glycolysis, STING phosphorylation, and type I IFN induction in tumor-infiltrating WT DCs." (PMID 36821379, 2023). "The HIF-1α function and glycolytic flux augmentation reciprocally regulated the NO and ROS production, strengthening the IFN-γ-activation signaling to induce nitrosative and oxidative stress and finally reducing tumor growth." (PMID 37965321, 2023). "Tumor growth beyond the original sufficient blood supply results in local hypoxia and the production and accumulation of numerous HIF‐1a molecules, which activate downstream molecules, including VEGF, FGF, and PDGF‐β to promote angiogenesis, tumor progression, and metastasis." (PMID 35933720, 2023). "Tumor cells were examined by Western blot assay to determine whether IL-6 knockout affects the role of sorafenib in regulating PFKFB3 and HIF-1α." (PMID 37476196, 2023). "Additionally, this nanomedicine combination can increase PDT sensitivity, and inhibit glycolysis by downregulating HIF-1α, which also lights up a new possibility for PDT-based gene therapy for tumor treatment." (PMID 36765543, 2023). "In the hypoxic region, the tumor cell secretes TGF-β and stimulates the HIF-1α pathway." (PMID 37594996, 2023). "Therefore, the ncRNA/HIF-1α/glycolysis-related enzyme signaling pathway may be a potential target for regulating the radiosensitivity of GC, and it may become a new direction to improve the radiosensitivity of GC by regulating tumor glucose metabolism and tumor microenvironment." (PMID 36909247, 2023). "Moreover, the analysis of tumor tissue showed a reduction in phospho-VEGFR2, supported by a decrease in HIF-1α and CD31 expression, indicating that Fuco-MnO2-NPs significantly compromised tumor angiogenesis." (PMID 37233501, 2023). "AhR, which—just as HIF-1α—belongs to the bHLH/PAS family of transcription factors, is important both for normal cell physiological processes and for tumor progression because AhR partakes in the molecular cascades that inhibit cell proliferation, differentiation, and apoptosis." (PMID 37305351, 2023). "Drugs known to repress HIF-1α expression indirectly, such as mTOR inhibitors, can also be used as adjuvant therapy for cancer because it has been shown in preclinical models of HCC that such treatment can suppress tumor growth." (PMID 37240068, 2023). "The processes by which tumours adapt to hypoxic conditions, including new vessel formation, cancer stem cell (CSC) regulation, glycolysis activation, and fatty acid metabolism, depend on the activation of hypoxia inducible factor (HIF)-1a." (PMID 37821935, 2023). "Furthermore, studies showed that a crosstalk between the expression of HIF-1α and HIF-2α in T-regs contributes to a tumor-suppressive activity." (PMID 37886168, 2023). "Hypoxia-induced factor-1α (HIF-1α), citrulline histone 3 (citH3) and CD66b expression in tumour and adjacent nontumor tissue samples was evaluated by western blotting, immunofluorescence and immunohistochemical staining." (PMID 37127629, 2023). "After 3 days of culture, tumor slices from MCF-7 xenografts showed a biomarker expression gradient with loco-regional change for the ER and HIF1α expression for all the tumor slices from six different xenograft tumors in the MF system but not in the PAC system." (PMID 36899943, 2023). "HIF-1α also upregulates the expression of the angiogenic growth factors such as vascular endothelial growth factor (VEGF), which in turn stimulates neovascularization, a fundamental process for tumor progression." (PMID 36599894, 2023).
tumor (continued). "Although previous researches have observed the elevated level of hypoxia in MES-like cells, the regulatory role of HIF-1A in MES-like cell or MES-like high tumor has not been illustrated." (PMID 36720864, 2023). "Moreover, it has been reported in three different tumour mouse models that antioxidants, as NAC and vitamin C, exert their antitumoural effect mainly acting on HIF-1α level." (PMID 36701089, 2023). "Under non-hypoxic or intermittent hypoxic conditions, wherein HIF-1α is dormant, NF-κB initiates tumor growth by enhancing reactive nitrogen species and ROS generation that cause damage and impart oncogenic characteristics." (PMID 36891273, 2023). "Notably, in macrophages from the hepatocellular carcinoma, HIF-1α-induced CA12 was positively correlated with glycolysis, which showed the ability to promote tumor regression in mice and was sufficient to synergistically enhance the anti-PD-1 therapy effects." (PMID 37828561, 2023). "In addition, the hypoxia microenvironment and tumor mTOR signal can stabilize or induce the expression of HIF-1α, respectively, and HIF-1α can induce the expression of CD39 and CD73." (PMID 37834375, 2023). "Hypoxia and HIF-1α-mediated signaling could induce the production of VEGF in TAM, suggesting that they could be a source of VEGF in the TME and could promote tumor angiogenesis." (PMID 37234993, 2023). "Our data from KEGG showed that five signaling pathways, including IL-17, HIF-1α, TLR4, NF-κB p65, and TNF signaling, may be the therapeutic pathways in the DOKD treatment of tumor development." (PMID 37239383, 2023). "To rule out the possibility that the size of the spheroids rather than the cell composition was affecting the HIF-1α expression, we compared the monoculture and 4-culture tumor spheroids having about the same size." (PMID 37519820, 2023). "HIF, composed of HIF-1α and HIF-2α, is considered the key controller of cellular responses to hypoxia and can contribute to an anti-apoptotic effect and facilitate drug resistance during tumor progression." (PMID 38062424, 2023). "At hypoxic tumor sites, HIF-1α activates MMP-2 and -9 to promote tumor metastasis." (PMID 37239383, 2023). "While HIF-1α is ubiquitously expressed in human tissues and upregulates the expression of glycolysis-related genes, HIF-2α is expressed in specific tissues, such as tumor vascular cells and macrophages, and promotes erythropoietin and iron metabolism." (PMID 36831085, 2023). "When the cultured tumor cells were treated with 1 μM B[a]P, there were no changes in mRNA expression of HIF-1α, its target genes, ARNT, AhR, and its target gene CYP1B1." (PMID 37305351, 2023). "HIF-1α interferes with immunosuppressive effects by regulating the expression of programmed cell death‐ligand 1 and CD73, resulting in anti-inflammatory effects on the tumour microenvironment." (PMID 37948404, 2023). "As previously reported, HIF-1α increases the expression of a wide range of immune checkpoints such as CTLA-4 on T cells; LAG3, TIM3, and PD-L1 on tumor cells; and PD-L1 and VISTA on MDSCs, thus resulting in the inhibition of T cell proliferation and T cell-mediated lysis." (PMID 37443821, 2023). "This is associated with bi-allelic inactivation of the von Hippel Lindau (VHL) tumour suppressor, which forms part of an E3 ubiquitin ligase complex that targets HIF-α subunits (HIF-1α and HIF-2α; also known as EPAS-1) for proteasomal degradation in the presence of oxygen." (PMID 36725335, 2023). "HIF1α, as the key factor in cell response to cellular hypoxia, stimulates inflammation and angiogenesis by increasing the synthesis of VEGF, which results in escalating tumor growth, aggressiveness and metastasis." (PMID 37686525, 2023).
tumor (continued). "Poor lymphocytic infiltration and low-TLS density were related with hypoxic background (higher HIF1a and LDH5 expression), metastasis to locoregional lymph nodes, a higher number of tumor buds in the invading front, and enhanced angiogenetic ability of the tumor." (PMID 36586079, 2023). "Although the EL-4 tumor mass in APN KO mice was smaller than that in WT mice, tumor-infiltrated BMSCs were two-fold higher in APN KO mice than those in WT mice and the infiltrated APN KO BMSCs maintained HIF1α expression, indicating that APN KO BMSCs highly migrate to tumor sites." (PMID 37370133, 2023). "Multiple studies suggest that, unlike in other cancers, HIF-2α is oncogenic while HIF-1α is tumor suppressive in ccRCC." (PMID 37460927, 2023). "HIF-1α increases neutrophil survival via supporting glycolysis (OXPHOS is not crucial for neutrophils) at initial stages, creating a chronic pro-inflammatory environment to support tumor progression." (PMID 37275901, 2023). "It was shown that histological grade (P = .002), HIF-1α (P < .001), VEGF-A (P = .034), and Ki67 (P = .009) were all risk factors, while tumor size, age, and FIGO stage were not risk factors affecting the efficacy of NACT (all P > .05)." (PMID 37335690, 2023). "Taken together, these results demonstrate that PFC@O2 treatment can alleviate tumor immunosuppression by downregulating the expression of HIF-1α and reducing the proportion of negative immune regulatory cells." (PMID 36675491, 2023). "KDM4A promotes HIF1α expression by inhibiting histone methylation in the HIF1α promoter region, thereby upregulating DDIT4 expression and activating the mTOR signaling pathway to promote tumor proliferation, migration, and invasion." (PMID 36611207, 2023). "It indicates that ESM1 may have a critical regulatory role in modulating tumor angiogenesis and progression in CSCC by interacting with VEGFα and HIF-1α." (PMID 37476182, 2023). "Furthermore, expression of miR-873-5p was increased, but that of HMOX1, HIF1α, and SPOP was reduced in the tumor tissue of mice treated with miR-873-5p agomir + oe-NC." (PMID 37382594, 2023). "Gene expression profiling of B20-sensitive and -resistant tumor endothelial cells also showed that both PPARG and HIF1α expression levels were higher (the difference was significant for HIF1α) in resistant endothelial cells compared with sensitive endothelial cells." (PMID 37100807, 2023). "In the absence of HIF-1α, tumor cells have difficulty in invading nearby tissues and growing in hypoxia." (PMID 37880686, 2023). "Knocking out or inhibiting HIF-1α significantly attenuated fibroblast activation by downregulating NF-ĸB signaling with significant reduction of CCL5, a potent pro-inflammatory chemokine and restricted tumor growth." (PMID 36986550, 2023). "Immediately after the hyperthermia treatment, the distinct repression of secreted pro-angiogenic factors (e.g., VEGF, PDGF-AA, PDGF-BB, M-CSF), intracellular HIF-1α and the enhanced phosphorylation of ERK1/2 in tumor cells were detectable (particularly for strong hyperthermia, 2D cell monolayers)." (PMID 37626752, 2023). "Indeed, a double knockout of HIF-1α and XPC resulted in the partial restoration of UV-induced tumor development in HIF-1α knockout mice." (PMID 36901857, 2023). "By stabilizing HIF-1α, lactate could enhance VEGF and Arg1 expression and induces M2-like polarization of TAMs, and VEGF and Arg1 support tumor growth via inducing neovascularization and providing substrates for cancer cell proliferation, respectively." (PMID 37564659, 2023). "In addition, under continuous stimulation with tumor antigen, hypoxia further induces TIM-3 and ITGIT to potentiate T cell exhaustion in a HIF-1α-independent manner." (PMID 36600243, 2023).
tumor (continued). "C/EBPδ inhibits FBXW7 in ER + cells, releasing HIF-1α and IL-6Rα expression and activating downstream STAT3 phosphorylation, promoting in vitro calmodulin transformation, sphere formation, and patient-derived xenograft (PDX) tumor metastasis." (PMID 37658431, 2023). "There were no noticeable differences in HIF-1α staining between different tumor stages within the histological subtypes." (PMID 37445752, 2023). "We find that hypoxia-induced HIF-1α activates the ALKBH5 axis and accelerates tumor metastasis." (PMID 36632222, 2023). "HIF1α promotes EMT through the enhancement of signaling pathways, including Snail, Twist, Notch, and β-catenin, thereby resulting in cancer cell invasion, migration, and tumor metastasis." (PMID 37046617, 2023). "HIF1α is usually inactivated in normal tissues, but it is usually stable in tumor cells, regardless of oxygen tension." (PMID 37790761, 2023). "Some studies suggest that hypoxia leads to the overexpression of hypoxia inducible factor-1α (HIF-1α), resulting in the upregulation of VEGF, which may induce tumor revascularization and local recurrence." (PMID 37139154, 2023). "Also, the stabilization of the HIF-1α and HIF-2α factors and the activation of their signaling pathways allows tumor progression via angiogenesis, the induction of autophagy, the expression of antiapoptotic factors, or the induction and stabilization of CSCs." (PMID 37046623, 2023). "Copper can even induce the expression of HIF-1α to promote rapid adaptation of tumor cells to hypoxic conditions when the microenvironment is not suitable for tumor growth." (PMID 37476384, 2023). "Pharmacodynamics study performed by estimating the transcript levels of Rac1, Cdc42, HIF-1α, β-catenin and DDX3 in the tumor tissue reveled a significant downregulation of these important metastasis markers in the combination group as compared to the drug alone group." (PMID 37024613, 2023). "In addition, western blotting and IHC staining were utilized to detect the protein levels of HIF‐1α and CA9 in tumor tissues from the nude mice in each group." (PMID 36537608, 2023). "Expression analysis of HIF-1α and HIF-2α on human ccRCCs and functional studies on human ccRCC cell lines have suggested HIF-1α as a suppressor and HIF-2α as a facilitator of invasive tumour behaviour." (PMID 37174052, 2023). "Furthermore, Western blot result showed that shNECAB3 greatly suppressed the protein levels of NECAB3, HIF-1α, and RIT1 in tumor tissues (P < 0.001)." (PMID 37215053, 2023). "Results from both HIF-1α immunohistochemical analysis and WB indicated that non-radioactive vascular embolization treatment resulted in more hypoxia area in tumor tissues." (PMID 37925456, 2023). "Also in HCC, HIF1α-induced expression of YTHDF1 drives ATG2A and ATG14 translation, two autophagy-related genes, promoting tumor progression." (PMID 37369946, 2023). "Although HIF-1α mediates the majority of adaptive changes in response to hypoxia conditions and is best studied, HIF-2 is connected to several signaling pathways, such as tumor invasion, angiogenesis, cell migration, and lipid metabolism regulation." (PMID 37626660, 2023). "Furthermore, HIF-1α siRNA was released to target the HNSCC hypoxic microenvironment that remodeled the immune microenvironment and suppressed tumor growth." (PMID 37292204, 2023).
tumor (continued). "Therefore, up-regulation of the HIF-1α/VEGFR/Akt/eNOS signaling axis, which activates eNOS expression, can increase NO production and promotion of tumor angiogenesis." (PMID 37400960, 2023). "Among most of these tumor types, a negative correlation between gene methylation and mRNA expression was revealed by calculating the Spearman correlation, including HIF1A, SLC16A1, UEVLD, SLC16A8, PFKFB2, LDHB, and SLC16A3." (PMID 37122693, 2023). "Other studies have shown that miR-21 expression may positively regulate HIF-1α by inhibiting VHL, further playing a role in promoting tumor angiogenesis by regulating the HGF/c-Met signaling pathway." (PMID 37316504, 2023). "We utilized the parental and HIF1α/HIF-2α DKO MDA-MB-231 cells to construct the orthotopic implantation tumor model and found AU1 could notably suppress the tumor growth in mice, as compared to tumors derived from mice in DMSO group." (PMID 36967443, 2023). "HIF-1a, VEGF, and TGF-b3 are well-known hallmarks of radioresistance in tumour cells." (PMID 37835511, 2023). "Our study lacked information on these signaling pathways and HIF‐1α expression because of the insufficient number of tumor specimens available for immunohistochemistry." (PMID 37605832, 2023). "Similarly, phosphorylated STAT3 in the nucleus enhances HIF-1α transcription, which in turn promotes the transcription of several proangiogenic genes such as VEGF, ultimately contributing to tumor angiogenesis." (PMID 36647454, 2023). "Experimental data show that propolis and some of its components have anti-angiogenic activity against neoplastic cells, decreasing the activation of hypoxia-inducible factor 1 (HIF-1α), and hence reducing vascularization induced by VEGF and consequently suppressing tumor growth." (PMID 37735586, 2023). "The pivotal role of STAT3 in tumor development stems from its capacity to regulate the transcription of genes involved in various key processes, such as the cell cycle (CCND1, CCNE1), metabolism (OCT1, HIF1A), and cell survival (BCL2, BCLXL, and HSP70)." (PMID 37474926, 2023). "TACE could enhance PD-1 and PD-L 1 expression in HCC, and induce tumor cell death with the release of tumoral antigens, proinflammatory cytokines, VEGF, and HIF-1α." (PMID 37368105, 2023). "The expression of HIF-1α in tumor center was increased compared with tumor periphery, however, the expression of HIF-1α has no significant change in tumor-beared RNF8+/+ and RNF8−/− mice." (PMID 37391451, 2023). "HIF-1α can stimulate the production of vascular endothelial growth factor (VEGF), which promotes angiogenesis and the formation of new blood vessels to supply the growing tumor." (PMID 37629778, 2023). "-Stimulates proliferation, migration, angiogenesis, and metastasis.-Induces epithelial–mesenchymal transition.-Induces and activates other signaling pathways in cancer cells such as JNK, Wnt, Notch, AKT/HIF1α, and TGF-β.-Creates barriers for T-lymphocytes to enter the tumor." (PMID 38003931, 2023). "Besides its function as inhibitor of HIF1α stability, PHD1 has either tumor promoting or suppressing activity depending on the cell and cancer type-specific signaling pathways." (PMID 36976352, 2023). "Under severe hypoxia (<1% O2), NF-kB is activated by HIF-1α to enhance the invasive nature of tumor cells at the rim of GBM, whereas c-MYC is upregulated by HIF-2α under moderate hypoxia (2.5–5% O2) to promote the proliferation of tumor cells in GBM." (PMID 37835592, 2023). "ESM1 can activate the downstream MAPK/ERK signaling pathway by binding to the c-Met membrane receptor of vascular endothelial cells and can promote the expression of HIF1α, VEGFA, MMP9, and other pro-angiogenic factors, thereby promoting tumor angiogenesis and peritoneal metastasis." (PMID 38201620, 2023).